MIF (macrophage migration inhibitory factor)
Diseases named in the same sentence as MIF in open-access papers (continued):
Sharing a sentence is not in itself a finding about the gene and the disease.
Sepsis (continued). "Conversely, the ghrelin-treated group had significantly lower MIF serum levels than the sepsis and vehicle groups." (PMID 39144689, 2024). "Serum MIF levels were significantly higher in the sepsis group than in the normal and sham groups (P <0.001)." (PMID 39144689, 2024). "Studies have shown that MIF recruits inflammatory cells by binding to receptors and is involved in the occurrence and development of sepsis." (PMID 39044269, 2024). "MIF also recruits peritoneal inflammatory macrophages for pathogens phagocytosis in an experimental poly-microbial sepsis model." (PMID 39416784, 2024). "The pleiotropic nature of MIF and its potential role in the pathogenesis of several diseases, such as sepsis, cancer, and autoimmune-related ailments, is evident from the extensive literature." (PMID 38915940, 2024). "The study found significantly higher tissue levels of MIF in the lung tissue of the sepsis and vehicle groups compared to the sham group." (PMID 37675176, 2023). "Both MIF and MIF-2 are abundantly expressed in adipose tissue and negatively associated with obesity; they may improve insulin resistance and promote wound repair; also, they are highly expressed in systemic inflammation and involved in the pathogenesis of sepsis." (PMID 38027963, 2023). "We also found that urine MIF was markedly lower in patients who died than in survivors of sepsis (p < 0.050)." (PMID 36631486, 2023). "To shed more light on the temporal changes of serum MIF in sepsis, in the present study we report its absolute levels on the initial days after ICU admission in septic patients, who were also divided into subgroups based on age, sex, and survival." (PMID 36631486, 2023). "In rats, supplementation of lysine significantly reduced the neutrophil, lymphocyte counts, the tumor necrosis factor alpha (TNF-α), interleukin-8 (IL-8), and migration inhibitory factor (MIF) levels and protected against sepsis-induced chronic lung injury." (PMID 36968283, 2023). "However, in most of the analyzed studies, the blood MIF level was measured only once on a single day in the patients, which did not allow us to assess the temporal kinetics of blood MIF level during the progression of sepsis and its association with the outcome of the disease." (PMID 36631486, 2023). "With subgroup analysis, we detected intersex difference in the kinetics of serum MIF in sepsis, since the decreasing trend in the survivors was present in males, but not in females." (PMID 36631486, 2023). "Despite of its limitations, our study highlights the biomarker value of serum and urine MIF kinetics for the prediction of the outcome of sepsis." (PMID 36631486, 2023). "In summary, we showed that an increasing serum MIF pattern was characteristic for patients who died in sepsis, whereas the level was rather decreasing in those who survived." (PMID 36631486, 2023). "Nevertheless, based on the present and previous findings, the changes in MIF levels alone or in combination with other biomarkers can be useful in the diagnosis of sepsis and in prediction of the outcome." (PMID 36631486, 2023). "The increasing serum levels of MIF seem to contradict the lower urine MIF levels in patients who died in sepsis, but it can be explained by the diverse source and complex role of MIF in inflammation." (PMID 36631486, 2023). "Macrophage migration inhibitory factor (MIF) has been considered as a biomarker in sepsis, however the predictive value of the pattern of its kinetics in the serum and in the urine has remained unclarified." (PMID 36631486, 2023). "Studies have shown that MIF participates in the occurrence and development of sepsis by recruiting inflammatory cells through receptor binding." (PMID 37919720, 2023). "MIF has emerged as a fascinating and versatile cytokine with a controversial role in various types of infections and sepsis." (PMID 38275363, 2023).
Sepsis (continued). "We report, to the best of our knowledge for the first time, that serum MIF level increased after ICU admission in those patients who died in sepsis, whereas it decreased in the survivors of the disease." (PMID 36631486, 2023). "The study showed that the Ticagrelor-treated group exhibited a greater decrease in the tissue lung levels of MIF compared to the sepsis and vehicle groups." (PMID 37675176, 2023). "Further research is needed to fully understand the role of MIF in sepsis and to develop effective treatments for this life-threatening condition." (PMID 38275363, 2023). "The sepsis group showed a significant increase in MIF levels in the lung tissue compared to the sham group." (PMID 37675176, 2023). "MIF is a pro-inflammatory cytokine that is rapidly released into the bloodstream in various inflammatory renal diseases, including sepsis." (PMID 37942584, 2023). "MIF has emerged as an important effector molecule for innate immunity in severe sepsis, e.g., melioidosis." (PMID 36758060, 2023). "We show that the patterns of serum MIF kinetics are different between patients who survived and who died in sepsis." (PMID 36631486, 2023). "Both ingoing and outgoing interaction strengths of C2_C1QA cells were increased in sepsis, with MIF-(CD74-CD44) displaying the most significant increase." (PMID 37919720, 2023). "These suggested that inhibition of MIF alleviated NLRP3 inflammasome mediated pyroptosis in sepsis-induced AKI." (PMID 35165294, 2022). "In this study, we focus on investigating the mechanism of MIF promoting pyroptosis in sepsis-induced AKI." (PMID 35165294, 2022). "MIF plays an important role in the occurrence and development of inflammatory diseases such as sepsis and acute respiratory distress syndrome." (PMID 35815289, 2022). "Although the role of MIF regulating NLRP3 inflammasome mediated pyroptosis in sepsis-induced AKI has been confirmed by our study, further studies will be continued in the future." (PMID 35165294, 2022). "This study demonstrated a novel mechanism of MIF regulating NLRP3 inflammasome mediated pyroptosis in sepsis-induced AKI." (PMID 35165294, 2022). "It has also been shown that serum MIF concentrations are higher in human patients with severe sepsis/endotoxic shock, and that these high levels correlate with disease outcome." (PMID 35464430, 2022). "In conclusion, MIF plays an effect of renal damage in sepsis-induced AKI, up-regulation of MIF in response to LPS stimulation promotes phosphorylation of p65 and finally aggravated NLRP3 inflammasome mediated cell pyroptosis." (PMID 35165294, 2022). "In conclusion, up-regulation of MIF in sepsis-induced AKI shows a renal damaged effect that aggravates NLRP3 inflammasome mediated cell pyroptosis through promoting phosphorylation of p65." (PMID 35165294, 2022). "The well characterized biological functions of D-DT are conferred to its proinflammatory activity in sepsis and favoring for tumorigenesis, the properties shared with MIF." (PMID 35965310, 2022). "Taken together, MIF promoted NLRP3 inflammasome mediated cell pyroptosis in sepsis-induced AKI via modulating NF-κB pathway." (PMID 35165294, 2022). "In summary, a solid experimental basis was provided in our study to explore the mechanism of MIF regulating NF-κB-NLRP3 pathway in sepsis-induced AKI." (PMID 35165294, 2022). "As far as we know, our study is the first one to reveal the mechanism of MIF promoting pyroptosis in sepsis-induced AKI." (PMID 35165294, 2022). "Sepsis patients showed an increase in a few of the pro-inflammatory cytokines i.e., IL-6, IL-8, IL-18, IL-33, IP-10, MIF, MIP1a, MIP1β, and MIP3a, along with the growth factors i.e., LEPTIN, GCSF, MCSF and ESelectin." (PMID 35681439, 2022). "MIF has been considered a necessary factor for NLRP3 inflammasome formation in sepsis and in systemic lupus erythematosus." (PMID 35165294, 2022). "Here, we aimed at clarifying the value of MIF as a sepsis biomarker with the meta-analysis of clinical trials." (PMID 33850259, 2021).
Sepsis (continued). "In more severe forms of sepsis, including fatal outcome, MIF levels are higher than in less severe forms." (PMID 33850259, 2021). "We previously demonstrated an increase in the macrophage migration inhibitory factor (MIF) in severe sepsis conditions, such as in the Vibrio vulnificus-infected model." (PMID 33771121, 2021). "Administration of recombinant MIF protein in a murine sepsis model increased mortality following LPS administration." (PMID 33407905, 2021). "Several experimental sepsis studies in mice showed that the neutralization of MIF reduced pro-inflammatory cytokine production and organ injury, and thereby increased the survival rate." (PMID 33407905, 2021). "A study with patients suffering from sepsis showed consistent results with higher ex vivo MIF release by PBMCs in patients versus healthy control subjects." (PMID 33407905, 2021). "Later, MIF was found in sepsis and autoimmune diseases and increased in the serum of patients with metabolic syndrome, and MIF was also involved in the formation of atherosclerosis." (PMID 35036405, 2021). "Under normal physiological conditions, MIF is constitutively expressed at a low level between 2–10 ng/mL, while the MIF concentration in human plasma fluctuates in response to stress stimuli such as sepsis, infection and different inflammatory disorders." (PMID 32545679, 2020). "As seen in our study, MIF levels in peritoneal fluid after sepsis induction are low, probably because we measured it 24 hours after CLP, but still, simvastatin treatments were capable to decrease it." (PMID 33110395, 2020). "Perhaps one of the best examples of how MIF can alter the immune response is that of sepsis, where inhibition of MIF has been demonstrated to inhibit the inflammatory cascade induced by LPS that would typically result in death." (PMID 32625208, 2020). "In patients suffering from sepsis MIF was found to be upregulated 5–10 fold, and higher MIF levels were found in individuals who ultimately died in comparison to those who lived." (PMID 32244916, 2020). "Results showed that TNF, HSPA1A, HSPA1B, TREM1, SOD2 and MIF genes related to sepsis correspond to m6A-cis-eQTLs." (PMID 32174955, 2020). "C5a stimulates neutrophils to produce MIF during sepsis, and C5a receptor inhibition decreases the release of MIF during the initial stages of sepsis." (PMID 31248381, 2019). "The sepsis inflammatory response has also been shown to be regulated by macrophage migration inhibitory factor (MIF)." (PMID 31281814, 2019). "T4 inhibited the migration inhibitory factor (MIF) in macrophages, and in agreement, low plasma T4 concentrations augmented plasma MIF levels in both patients and rats with severe sepsis." (PMID 31214123, 2019). "Macrophage migration inhibitory factor (MIF) is known as a pleiotropic inflammatory cytokine and has been recognized as a mediator of a number of inflammatory diseases including sepsis and atherosclerosis." (PMID 29027966, 2017). "Anti-MIF antibodies have been shown to be protective against endotoxemia, arthritis sepsis and OVA-induced allergic asthma." (PMID 26752192, 2016). "In patients with severe sepsis, low plasma T4 concentrations were inversely correlated with plasma MIF concentrations." (PMID 26858715, 2016). "In experimental sepsis models, MIF inhibition by MIF antibodies and MIF receptor antagonists was shown to protect from septic shock and to improve survival." (PMID 27313864, 2016). "Increased expression and secretion of MIF has been reported in several acute and chronic inflammatory diseases such as sepsis, arthritis, asthma and lung cancer patients with COPD." (PMID 26752192, 2016). "Macrophage migration inhibitory factor (MIF) is a proinflammatory cytokine implicated in acute and chronic inflammatory conditions, including sepsis, autoimmune disease, atherogenesis, plaque instability, and pulmonary arterial hypertension." (PMID 26858715, 2016).
Sepsis (continued). "Macrophage migration inhibitory factor (MIF) is an important mediator of severe sepsis and septic shock." (PMID 27313864, 2016). "T4 has been shown to be a potent natural inhibitor of MIF, and that plasma MIF and fT4 concentrations are inversely correlated in patients with severe sepsis." (PMID 26318747, 2015). "Elevated levels of MIF were subsequently found in the plasma of patients with sepsis and septic shock and were positively correlated with the sepsis severity." (PMID 25821355, 2015). "Since MIF is a mediator of inflammatory cell recruitment and MIF plasma levels are known to be elevated in inflammatory diseases like arthritis or sepsis, we analyzed parameters of inflammation in ESRD patients and controls." (PMID 26485680, 2015). "Recently, antibodies specific to β-sheet structure containing the oxidoreductase motif of MIF have been demonstrated for their protective effects in sepsis model or contact hypersensitivity." (PMID 24424397, 2014). "In this perspective, neutralizing MIF activity by using antibodies or gene knockout, protected mice against severe sepsis by E. coli and Pseudomonas and also enhanced P. aeruginosa airway clearance." (PMID 25503271, 2014). "Elevated levels of MIF have been detected in sepsis as well as numerous infectious diseases with exaggerated immune response such as dengue hemorrhagic fever and influenza virus infection." (PMID 24424397, 2014). "Several previous studies showed the advantage of targeting MIF for treating inflammatory conditions such as sepsis and asthma." (PMID 25329068, 2014). "MIF is a pleiotropic cytokine broadly studied in sepsis and many infectious and auto-immune diseases." (PMID 25050663, 2014). "Serum MIF concentration of patients suffering from sepsis are significantly higher compared to healthy individuals and correlate with the outcome." (PMID 23853427, 2013). "While this autocrine/endocrine function has been previously illustrated in sepsis and ischemia/reperfusion injury, the overall cardiac effects of MIF are challenging as both protective and deleterious consequences have been reported." (PMID 23536817, 2013). "In the largest genetic study of sepsis performed to date, MIF alone among 20 candidate polymorphic loci within immune response genes was associated with clinical outcome from septic shock." (PMID 23853427, 2013). "Elevated serum levels of MIF were detected in many infectious and inflammatory diseases, such as rheumatoid arthrits, sepsis, vasculopathy, viral hepatitis, HIV infection and malaria, indicating that MIF is implicated in pathogenesis." (PMID 23451183, 2013). "Levels of MIF, a proinflammatory cytokine that plays a critical role in the development of sepsis, decreased in T4-administrated mice as compared with the control mice." (PMID 22844479, 2012). "In sepsis, inhibition of the MIF pro-inflammatory activity has previously proven beneficial in numerous animal models of endotoxemia, and gram-negative and gram-positive septic shock." (PMID 22506003, 2012). "In mice models of endotoxic shock or E. coli peritonitis, elevated serum MIF was detected, and MIF neutralizing antibodies protected the mice from lethal shock and sepsis." (PMID 23319831, 2012). "MIF levels peak earlier and show a distinct dose/time response compared to other inflammatory and sepsis markers." (PMID 22506003, 2012). "In this scenario, MIF seems to compromise host protection by exacerbating intestinal tissue damage and by inducing a sepsis-like response." (PMID 21977228, 2011). "Considering the critical role of MIF in the pathogenesis of experimental sepsis, we investigated several markers of systemic inflammation in T. gondii-infected wt and Mif−/− mice." (PMID 21977228, 2011). "MIF level was elevated in tissue and serum in a mouse sepsis model and also increased in the serum of patients with septic shock." (PMID 21197406, 2010).
Sepsis (continued). "The released MIF modulates the expression of proinflammatory mediators, leading to early death in patients with sepsis." (PMID 20939898, 2010). "In different experimental models of sepsis, blocking MIF activity, either through MIF gene disruption or with anti-MIF antibodies, reduces cytokine production by downregulating TLR4 expression." (PMID 22046508, 2010). "Macrophage migration inhibitory factor (MIF), an upstream proinflammatory regulator, increases the inflammation caused by sepsis." (PMID 20939898, 2010). "Earlier studies showed that recombinant MIF increased mortality during E. coli sepsis when co-injected with bacteria in mice." (PMID 20169062, 2010). "Macrophage migration inhibitory factor (MIF) has emerged as a pivotal mediator of innate immunity and has been shown to be an important effector molecule in severe sepsis." (PMID 20169062, 2010). "The molecular mechanism of MIF inhibition in decreasing deleterious cytokine activity during sepsis is currently under investigation." (PMID 20939898, 2010). "Recently it was shown that blood concentrations of MIF are elevated in patients with sepsis and able to predict early mortality." (PMID 20169062, 2010). "Macrophage migration inhibitory factor (MIF), an important proinflammatory cytokine, is a critical mediator of innate immunity and is implicated in the pathogenesis of sepsis." (PMID 20939898, 2010). "The neutralization of MIF results in an attenuation of the inflammatory response and improved survival in experimental sepsis." (PMID 20847814, 2010). "Serum level of MIF was also significantly elevated in patients with sepsis induced acute lung injury." (PMID 21197406, 2010). "In the light of these observations, the relationship between TRX1 and MIF in sepsis is of great interest." (PMID 20847814, 2010). "The plasma levels of MIF were significantly elevated at the time of diagnosis of sepsis, compared with levels in the postoperative and volunteer groups." (PMID 20847814, 2010). "In light of the proinflammatory properties attributed to MIF in sepsis, we studied the expression and function of MIF in a well-established mouse model of melioidosis." (PMID 20169062, 2010). "Previous own results showed elevated MIF plasma levels in patients with severe sepsis as well as in patients with systemic inflammation compared to healthy controls." (PMID 19941661, 2009). "Macrophage migration inhibitory factor (MIF) is an important mediator of inflammatory responses and a drug target for sepsis and auto-immune diseases." (PMID 19564921, 2009). "MIF has immunoregulatory functions in sepsis, ARDS, bronchial asthma, rheumatoid arthritis and tumorgenesis." (PMID 19413900, 2009). "Circulating MIF levels are correlated with sepsis severity scores, presence of shock, disseminated intravascular coagulation, urine output, blood pH, and lactate and cytokine levels." (PMID 19941661, 2009). "Plasma MIF concentrations are elevated in patients with inflammatory diseases such as sepsis, ARDS or rheumatoid arthritis." (PMID 19413900, 2009). "The present study investigated for the first time the association of the MIF -173 promoter SNP and the MIF -794 CATT5-8 microsatellite with the incidence and outcome of severe sepsis by the comparison with two control groups." (PMID 19941661, 2009). "An increase in MIF in critically ill patients and a correlation between serum MIF and early death in patients with severe sepsis have previously been reported." (PMID 20021698, 2009). "Apart from its critical role in sepsis through potentiating septic shock, MIF is a pituitary-derived antagonist of glucocorticoids." (PMID 19558639, 2009). "In fact, an administration of neutralizing anti-MIF antibodies has proven therapeutically effective in animal models of sepsis and in LPS-induced lung injury models." (PMID 19413900, 2009).